TRPM7 (transient receptor potential cation channel subfamily M member 7)
Diseases named in the same sentence as TRPM7 in open-access papers (continued):
Sharing a sentence is not in itself a finding about the gene and the disease.
cancer (continued). "The TRPM7 was thought to be a target of lidocaine in some types of cancer." (PMID 33435261, 2021). "For example, TRPM7 is overexpressed and promotes cancer cell proliferation in bladder cancer." (PMID 33435261, 2021). "Other Ca2+-toolkit proteins implicated in various cancers include calcineurin, SERCA pumps, SPCAs, PMCAs, the IP3R, RyRs, STIM proteins, T-Type VGCCs, TRPC1, TRPC3, TRPC6, TRP ion channel melastatin 2 (TRPM2), TRPM7 and TRPM8." (PMID 36046118, 2021). "The positive correlation between tumour progression and TRPM7 expression may result from the role of TRPM7 in cancer development." (PMID 33617107, 2021). "While very little is known about MagT1 in cancer, much more is known about TRPM7." (PMID 34067290, 2021). "As such our findings with TRPM7 could suggest a therapeutic target for combinational cancer treatment." (PMID 34627839, 2021). "This indicates that the TRPM7 calcium channel activity may contribute in the growth of MCF-7 cancer cells via calcium influx." (PMID 34944940, 2021). "Melastatin-like transient receptor potential 7 (TRPM7) ion channels play a role in cancer and may be a target for lidocaine." (PMID 33435261, 2021). "In harmony with the findings obtained in previous studies that TRPM7 supports cell proliferation and tumor growth in various cancer cell lines, in our series, tumor size was significantly greater in patients with high TRPM7 expression than those with low expression." (PMID 34938330, 2021). "Preliminary studies have demonstrated that in addition to its physiological functions, TRPM7 may play a key role in cancer by regulating cellular proliferation, migration, and invasion in cancer cell lines." (PMID 34938330, 2021). "The melastatin-like transient receptor potential 7 (TRPM7) ion channel is aberrantly expressed in some cancers and may play a role in the disease." (PMID 33435261, 2021). "Abnormal expression of TRPM7 is frequently observed in various cancers, including BC." (PMID 34285910, 2021). "Indeed, several reports have suggested a role for TRPM7 in cancer proliferation, migration, and invasion." (PMID 34936030, 2021). "TRPM7 overexpression in bladder cancer cells promoted the proliferation of cancer cells." (PMID 34950031, 2021). "Collectively, these studies suggest that TRPM7 may represent a good therapeutic target to prevent a metastatic cancer cell phenotype." (PMID 32825277, 2020). "For example, upregulated TRPM7 in pancreatic, breast, ovarian, and bladder cancers is correlated with tumour progression and aggression as well as poor overall survival of cancer patients, suggesting a protumour effect of TRPM7." (PMID 32575381, 2020). "TRPM7 plays diverse oncogenic roles in a variety of cancers." (PMID 32643506, 2020). "Although numerous studies support that TRPM7 is involved in cancer cell migration and invasion, the precise understanding of the TRPM7 signaling pathway that modulates the molecular process of cancer cells remains unclear." (PMID 32907556, 2020). "In addition, we investigated the importance of TRPM7 in cancer growth by treatment with the TRPM7 inhibitor, carvacrol." (PMID 32907556, 2020). "Moreover, hypoxia-induced ATP depletion stimulates TRPM7 activity, which facilitates cancer cell migration via activation of m-calpain and focal adhesion turnover." (PMID 32825277, 2020). "However, TRPM7 is also active in several types of cancers in humans, and blocking the expression of this pathway leads to a decrease in the proliferation, migration, and invasion of cancer cells." (PMID 32168794, 2020). "With this regard, we can view TRPM7 as a key regulator of cancer growth, migration, and invasion." (PMID 32643506, 2020). "TRPM7 channel inhibition in cancer cells is almost unequivocally beneficial for disease outcome." (PMID 32887220, 2020). "Furthermore, TRPM7 channel is involved in a variety of diseases including neurological disorder, cancer, tooth pain, etc." (PMID 32643506, 2020).
cancer (continued). "Cancer cells often accumulate these ions through TRPM7 activity." (PMID 32887220, 2020). "TRPM7 is among the most thoroughly examined TRP channels in cancer." (PMID 32887220, 2020). "As both RPSA and TRPM7 are overexpressed and regulate cancer cell migration, it is tempting to speculate that these two biomarkers could interact in PDAC." (PMID 32733880, 2020). "Moreover, TRPM7 has been linked to epithelial–mesenchymal transition (EMT, a key process underlying cancer cell motility and metastasis) in numerous cancers." (PMID 32825277, 2020). "Several studies also showed a role of TRPM7 kinase domain in cancer cell migration." (PMID 32733880, 2020). "Together, these studies suggest that dysregulation of TRPM7 is important in cancer stem cell regulation and that TRPM7 may be a therapeutic target for oncogenesis." (PMID 30995736, 2019). "The involvement of TRPM7 in cancer development is increasingly recognized." (PMID 30615643, 2019). "Recent evidence indicates that cancer stem cell regulation involves TRPM7-dependent pathways." (PMID 30995736, 2019). "Furthermore, TRPM7 is known to be aberrantly expressed in human cancers and playing roles in tumor growth and metastasis." (PMID 31293101, 2019). "Moreover, the pharmacological inhibition or silencing of TRPM7 inhibits adhesion or invasion in cancer cell lines as well as migration of HMEC." (PMID 30279961, 2018). "Activation of TRPM7 and Hsp90a secretion could be linked to MMP-2 secretion which is an important step to degrade surrounding ECM and initiate cancer cell invasion." (PMID 29772843, 2018). "Silencing of TRPM7 in PDAC cell lines leads to a reduction of cancer cell invasion." (PMID 29772843, 2018). "TRPM7 is emerging as a key player in cancer growth, migration and invasion." (PMID 28810912, 2017). "TRPM7 is a ubiquitously expressed ion channel with intrinsic kinase activity that plays regulatory roles in a variety of cellular processes, physiological responses, early development, organogenesis, and human diseases, particularly cancer." (PMID 28379203, 2017). "Results of these studies suggest the mechanisms that mediate TRPM7-induced cell death may depend on the cell types; however, they support a role of TRPM7 in promoting survival of cancer cells and tumor growth." (PMID 28379203, 2017). "Downregulation of TRPM7 in human cancer cells impaired cell migration and invasion; these effects could be reversed by Mg2+ supplementation." (PMID 28379203, 2017). "Furthermore, the aberrant expression and/or activity of TRPM7 in malignant tumors offer the opportunity of targeting TRPM7 for treatment of patients with cancer." (PMID 28379203, 2017). "In certain carcinoma examined, TRPM7 is aberrantly over-expressed in cell lines and/or tissues." (PMID 28379203, 2017). "Although mammalian TRPM7 is well characterized biophysically and its pivotal role in cancer, ischemia and cardiovascular disease is becoming increasingly evident, the study of TRPM7 in mouse models has been hampered by embryonic lethality of transgenic ablations." (PMID 27628598, 2016). "However, if their concentrations increase, enzyme activity of PLC would be lowered significantly and meaningfully by the cations under the specific conditions such as expression of TRPM7, G2 cell cycle phase or in cancer cells." (PMID 26658739, 2015). "TRPM7 overexpression was found in tissues of several cancer types." (PMID 25913706, 2015). "Therefore, TRPM7 can potentially serve as both a clinical biomarker and therapeutic target in a variety of cancers." (PMID 25965832, 2015). "Besides, results of multiple studies showing the proliferative and pro-invasion roles of TRPM7 in cancer cells suggest that targeting TRPM7 offers an opportunity of developing new anti-tumor therapies." (PMID 25079291, 2014).
cancer (continued). "The evidence showing over-expression of TRPM7 in cancer tissues and cell lines suggests that these ion channels have the potential of being developed into cancer biomarkers for prevention, early detection, prognostication, and predicting/monitoring therapeutic responses." (PMID 25079291, 2014). "However, the signaling pathways and the mechanisms that mediate the various cellular effects of TRPM7 in cancer cells remain to be determined." (PMID 25079291, 2014). "In this article, we will provide an updated review of the structural features and biological functions of TRPM7, present a summary of current knowledge of its roles in development and cancer, and discuss the potential of TRPM7 as a clinical biomarker and therapeutic target in malignant diseases." (PMID 25079291, 2014). "The concentration of BZs at which they act as TRPM7 blockers and proliferation inhibitors, may be too high for application in cancer therapy." (PMID 23426784, 2013). "We propose that the present results, showing the proliferation-inhibitory activity of midazolam, not only lay a theoretical foundation for the preferential use of midazolam as the anesthetic during tumorectomy, but also identify TRPM7 as a therapeutic target for cancer." (PMID 23426784, 2013). "Furthermore, our results suggest that four of these genes - ADCK2, PRKAR2B, TRIB2 and TRPM7 - seem to regulate HIF-1α accumulation in multiple cancer cell lines." (PMID 22355351, 2012). "Overall, the results elucidated that targeting TRPM7 could modulate the glycolytic cancer pathway." (PMID 40813985, 2025). "Given that TRPM7 is overexpressed in numerous types of cancers, and involved in cell proliferation, migration and invasion, it is tempting to speculate that the PACT complex may play a significant role in cancer cell fates by regulating their intracellular Mg2+ levels." (PMID 41395111, 2025). "Moreover, TRPM7 kinase domain is required for carcinogenesis and cancer cell dissemination in vivo." (PMID 40274768, 2025). "Consequently, TRPM7 has been proposed as a new anti-cancer drug target." (PMID 39513908, 2024). "Inhibition of the TRPM7-dependent glycolysis could be harnessed for cancer therapy." (PMID 36878949, 2023). "Similarly, knocking down TRPM7 in pancreatic cancer cells inhibited cancer cell migration." (PMID 36064388, 2022). "Moreover, upregulation of TRPM7 expression serves as a powerful indicator of clinicopathological features related to relatively poor clinical outcomes for individuals with various types of cancers." (PMID 34285910, 2021). "When previous studies and our findings are evaluated together, it can be implicated that TRPM7 supports the EMT process by changing i-Ca2+ levels through the PI3K/AKT pathway and is associated with aggressive biological behaviour, metastasis, and poor survival in various cancers including GC." (PMID 34938330, 2021). "Recently, new knowledge pertaining to TRPM7 has emerged, linking it to cell proliferation, survival, and development, and identifying its role as a pathophysiological modulator in several disease conditions such as ischemic stroke, hypertension, defective ossification, and cancers." (PMID 32168794, 2020). "Thus, targeting of TRPM7/RPSA complexes could be a promising strategy to reduce cancer cell migration in the neoplastic pancreas." (PMID 32733880, 2020). "TRPM7 is found to be more highly expressed in some types of human cancer tissue compared to adjacent non-tumor tissue and is thought to be associated with cancer development." (PMID 31947967, 2020). "Thus, we can say that the different mechanisms that play a role in cancer biology may contribute to the reduction of TRPM7 immunoreactivity in our EC groups." (PMID 30997980, 2019). "Whether EGFR inhibitors also influence TRPM7 in cancer patients is unclear." (PMID 30995736, 2019). "Therefore, TRPM7 may be considered a prometastatic protein and an important player in Ca2+ driven dissemination of cancer." (PMID 30615643, 2019).
cancer (continued). "Proliferation of cancer cells depend on TRPM7-mediated Mg2+ influx since cellular levels of Mg·ATP and Mg-bound metabolites have to be duplicated during cell division, and so the Mg2+-dependent process would likely be primarily affected by the ablation of TRPM7 in such cells." (PMID 30770447, 2019). "In this article, I will provide a review of the expression of TRPM7 in cancer, the roles of TRPM7 in cancer cells including proliferation, survival, migration, invasion, and epithelial-mesenchymal transition, as well as the role of TRPM7 in tumor growth and metastasis." (PMID 28379203, 2017). "Knockdown of TRPM7 could reverse EMT markers in the three BCa cells, and we also observed that TRPM7 deficiency could also inhibit migration and invasion of BCa cells, as EMT has been reported to play a critical role in cancer cell migration and invasion." (PMID 27662662, 2016). "Therefore, TRPM7 might be part of a mechanosensing complex adopted by cancer cells to drive cancer metastatic phenotypes." (PMID 23594099, 2013). "mRNA expression of MHG was positively correlated with CNV in most cancers, such as SLC41A1, CNNM2, and TRPM7 in SKCM, LUAD, SARC, BRCA, LUSC and OV (P < 0.05)." (PMID 41174507, 2025). "Among them, transient receptor potential melastatin 7 (TRPM7) is a MS TRP ion channel, whose expression is notably altered in various cancers." (PMID 40083943, 2025). "TRPM7 silencing decreased the EGF-induced migration, invasion and wound healing of cancer cells in vitro and metastasis formation in mice in vivo." (PMID 38255793, 2024). "The downregulation of TRPM7 reversed the EMT status, inhibited the proliferation, migration and invasion of cancer cells, and promoted cell cycle arrest at the G0/G1 phase and apoptosis." (PMID 38255793, 2024). "Increasing evidence suggests that increased activation of TRPM7-mediated MAPK/ERK and PI3K/AKT signaling pathways are critical components of tumorigenesis and other signature cancer features." (PMID 38680092, 2024). "Here, through an integrated set of approaches, we identified the transient receptor potential melastatin 7 (TRPM7), a member of the TRP channel superfamily, as a gatekeeper of cellular glycolysis in glycolytic cancer and endothelial cells." (PMID 36878949, 2023). "In the following section, we provide an overview of how Piezo1/2, TRPC1, TRPC5, TRPM2, TRPM4, TRPM7, TRPV2 and TRPV4 affect cancer cell behavior." (PMID 36158191, 2022). "In human breast ductal adenocarcinoma (hBDA), the high levels of TRPM7 expression have been interconnected with the Ki67 proliferation index, Scarff-Bloom-Richardson (SBR) cancer grade, and tumor size." (PMID 36844925, 2022). "In particular, TRPM7, a member of the TRP family, is important in cancer cell biology because it mediates calcium and magnesium flows." (PMID 36363540, 2022). "In particular, we discuss the roles of Piezo1/2, TRPC1, TRPC5, TRPM2, TRPM4, TRPM7, TRPV2, and TRPV4 in mechanosensing and cancer metastasis." (PMID 36158191, 2022). "Recent collectively hinted potential links between cancer metastasis and the nuclear factor of activated T (NFAT)/ TRPM7/calcineurin signaling in HNSCC." (PMID 35771152, 2022). "As Ca2+ is an important regulator of cell cycle and proliferation, TRPM7, which is a special member of the TRP channels known to be permeable to Ca2+ and Mg2+, is thought to be highly important in terms of cancer cell biology." (PMID 34938330, 2021). "Previous studies have demonstrated that the inhibition of TRPM7 inactivates ERK or AKT signaling events and thereby influences various cancer cellular fates." (PMID 34285910, 2021). "It is also reported to influence cell motility and invasion by activating ERK1/2, and previous reports have demonstrated that TRPM7 positively controls oncogenic AKT events to orchestrate the tumorigenesis, invasion, and metastasis of various cancers." (PMID 34285910, 2021).
cancer (continued). "TRPM7 is a featured member of the TRPM family and has managed to attract the attention of cancer researchers in recent years." (PMID 34938330, 2021). "Beyond TRPM7, other melastatin-related TRP family receptors with putative roles in cancer progression are TRPM1 and TRPM8." (PMID 32825277, 2020). "In previous studies, TRPM7 has been reported to regulate cell migration and invasion through the MAPK pathway, as well as the PI3K/Akt, ERK, and JNK pathways in cancer." (PMID 32907556, 2020). "Epithelial-mesenchymal transition is involved in fibrosis and cancer metastasis and involves EGF activation, effects attenuated by TRPM7 siRNA by mechanisms involving ERK1/2 and STAT3." (PMID 30995736, 2019). "Hypoxia can be sensed by several TRP channels such as TRPM7 and TRPA1, TRPC1, TRPC6, both in cancer cells and in stromal cells." (PMID 29772843, 2018). "Chemical modulators of TRPM7 channel produced inhibition of proliferation, growth, migration, invasion, invadosome formation, and markers of EMT in cancer cells." (PMID 28379203, 2017). "Functional expression of TRPM7 plays a regulatory role in epithelial-mesenchymal transition (EMT), which represents a tumor microenvironment-induced invasive phenotype adopted by cancer cells in metastasis." (PMID 28379203, 2017). "The focus of our basic research studies is to determine the signaling mechanisms that mediate the proliferative and migratory roles of TRPM7 and TRPM8 in pancreatic epithelia and cancer cells." (PMID 24278689, 2012). "In addition, research has shown that TRPM7 regulates the hypoxia-inducible factor 1α (HIF-1α)-driven pathway by activating AMPK, which supports cancer progression and metastasis, by facilitating the formation of abnormal blood vessels that stimulate VEGF." (PMID 40813985, 2025). "In a clinical point of view, we confirmed that PAK1 is overexpressed in PDAC tissues by analyzing the TCGA-PAAD/GTEX GEPIA transcriptomic database while TRPM7 transcriptomic expression was not significantly different between cancer and non-cancer tissues." (PMID 40274768, 2025). "In contrast, TRPM7 is up-regulated in CRC tissues and promotes the proliferation and invasion of CRC cells by facilitating the EMT process.The expression levels of TRPM6 and TRPM7 also affect the drug resistance of cancer cells." (PMID 39633507, 2024). "It is worth noting that TRPM7 may be related to the drug resistance of GBM, which induces the increase of cancer stem cell marker ALDH1 activity." (PMID 39633507, 2024). "When it comes to cancer, the most studied TRPM channel in relation to metastases is TRPM7." (PMID 36837670, 2023). "Recent studies have shown that TRPM7 is expressed more highly in cancer tissues than non-cancerous tissue, and its pattern is associated with clinical characteristics in many cancers." (PMID 36363540, 2022). "Additionally, TRPC1, TRPC5, TRPM2, TRPM4, TRPM7, TRPV2 and TRPV4 can independently induce EMT in cancer cells." (PMID 36158191, 2022). "Furthermore, we evaluated TRPM7 and NFATC3 expression in the Gene Expression HNSCC cohort by using the TCGA online open access cancer microarray platform." (PMID 35771152, 2022). "Actually, many scientific pieces of paper claim a role of TRPM7 in CRC and other cancers." (PMID 33923883, 2021). "TRPM7 inhibits the AKT and ERK pathways to promote malignancy in cancers." (PMID 34285910, 2021). "TRPM7 is a non-selective cation channel with notable permeability to Ca2+ and Mg2+, though it specifically facilitates Ca2+ influx in various cancer cells." (PMID 33726758, 2021). "Although PAC-1 has been previously shown apoptosis-inducing activity in several cancer cell lines at concentrations less than or equal to 10 μM, it did not induce the apoptosis of T-REx-293 cells expressing TRPM7 at 10 μM concentration in the present study." (PMID 30538170, 2019). "The melastatin-related transient receptor potential 7 (TRPM7) regulates a non-selective cation channel and promotes cancer metastasis." (PMID 30819230, 2019).